KRAS (KRas proto-oncogene, GTPase)
Diseases named in the same sentence as KRAS in open-access papers (continued):
Sharing a sentence is not in itself a finding about the gene and the disease.
pancreatic cancer (continued). "KRAS mutations are the most common genetic mutations in pancreatic cancer." (PMID 37773552, 2023). "In pancreatic cancer cells, as a representative KRAS-mutated tumor entity, targeting WEE1 induced sensitization to radiation with a DER of 1.3 ± 0.1 in MiaPaCa-2 cells and gemcitabine chemoradiation in vitro and in vivo through inhibition of the HR repair pathway and abrogation of the G2 checkpoint." (PMID 36313934, 2023). "In particular, PANC-1 could be inhibited by Autora Kinase inhibitors, as this is suggested as a potential strategy for pancreatic cancers harboring KRAS mutations." (PMID 37371811, 2023). "Sotorasib (AMG510), a selective and irreversible small-molecule suppressor targeting the KRAS G12C mutation, has shown promising antitumor effects in non-small-cell lung cancer (NSCLC), as well as other solid tumors, especially pancreatic cancers with the KRAS G12C mutation." (PMID 37313463, 2023). "More recent reports described the use of exosome-derived DNA, which arises from viable pancreatic cancer cells, demonstrating that increased occurrence of KRAS mutations in exosome-derived DNA was a predictor of progression-free survival and OS and correlated with disease progression." (PMID 37627202, 2023). "However, recent discoveries in the main biological event in pancreatic carcinogenesis, the KRAS mutation, have broadened our understanding of pancreatic cancer and opened a window of opportunity." (PMID 37894382, 2023). "For instance, pancreatic cancer cells thrive in hypoxic and nutrient-deficient environments because of enhanced metabolic reprogramming driven by oncogenic KRAS, which leads to increased glucose uptake, enhanced glycolysis, and lactate production in the presence of oxygen." (PMID 37242560, 2023). "Hence, by interrupting KRAS calmodulin-binding, prostatin (a PKC activator) elevates the level of Fzd8, which prevents KRAS mutation in pancreatic cancer cells." (PMID 36975494, 2023). "Similarly, the poor prognostic implications of a KRAS mutation is more a reflection of the underlying cancer types (5 of 10 being pancreas cancer) as is potentially, the better outcomes associated with prior platinum therapy." (PMID 37365284, 2023). "In pancreatic cancer, KRAS is the most frequently mutated oncogene." (PMID 36765737, 2023). "However, the Q61R KRAS mutation was identified in both the previous pancreatic cancer and the current liver tumor, leading us to conclude that the pancreatic cancer had mutated completely into SCC that formed a liver tumor." (PMID 37773552, 2023). "Approximately 90% of pancreatic tumors present with mutated KRAS." (PMID 37408249, 2023). "Although KRAS mutations are present in the majority of pancreatic cancers, the nature of the KRAS mutation, the presence of additional mutations with lower prevalence and the molecular subtype all have the potential to alter dependency on cell signalling pathways." (PMID 36977556, 2023). "KRAS gene mutation is considered to be an important driver of pancreatic cancer." (PMID 37713870, 2023). "Finally, KRAS G12C inhibitors have been recently tested in patients with pancreatic cancer with relative success, and inhibitors of KRAS harboring other mutations are under clinical development." (PMID 37894382, 2023). "Moreover, numerous studies have revealed that the KRAS mutation adversely influenced the outcomes of patients with pancreatic cancer." (PMID 37333498, 2023).
pancreatic cancer (continued). "Additionally, KRAS mutation ranks among the most prevalent oncogenic events, occurring in approximately 90% of pancreatic cancer patients." (PMID 37628967, 2023). "As mutant KRAS can interfere with siRNA-mediated gene silencing in pancreatic cancer cells, the presence of KRAS mutations in EGI-1 cell lines could have resulted in impaired siRNA-mediated gene silencing." (PMID 37920204, 2023). "Research is ongoing to develop effective therapies for KRAS mutations in pancreatic cancer." (PMID 37242560, 2023). "In pancreatic cancer, the molecular mechanisms of cigarette smoking are currently unknown; however, a synergic role of nicotine metabolites and rare mutations (i.e., KRAS mutations) has been proposed." (PMID 37346070, 2023). "Moreover, increased LDL-R expression has been observed in all stages of KRAS mutant pancreatic cancer and is associated with increased disease recurrence rates." (PMID 36675307, 2023). "KRAS G12D is the most common KRAS gene mutation in pancreatic cancer, accounting for about 41%." (PMID 37686343, 2023). "Approximately 90% of pancreatic cancer (PC) contain KRAS mutations." (PMID 37503215, 2023). "Compound is a highly active helicoid KRAS-PDEδ inhibitor that down-regulates the phosphorylation of key proteins Erk and Akt in the downstream pathway of KRAS, and induces the apoptosis of KRAS-mutated pancreatic cancer cell lines." (PMID 37669923, 2023). "Pancreatic cancers are linked to the KRAS gene’s oncogenic mutations in approximately 90% of cases." (PMID 37371705, 2023). "In addition, activated EGFR coupled with KRAS mutation drives increased EV uptake in pancreatic cancer cells through micropinocytosis." (PMID 37823055, 2023). "On the other hand, oncogenic Kirsten rat sarcoma viral oncogene homolog (KRAS) mutation in pancreatic cancer might promote mitochondrial division and activation of DRP1, which are essential to KRAS-driven cancer progression." (PMID 37525297, 2023). "In a recent study, we also found that the inhibition of GRP78 by YUM70 could suppress oncogenic KRAS protein expression and reduce the viability of lung, colon, and pancreatic cancer cells bearing various KRAS mutations." (PMID 37243204, 2023). "Based on the combinatorial effect of KV with oxaliplatin, this compound may be an effective combinatorial therapeutic agent for the treatment of KRAS-mutated pancreatic cancer." (PMID 37174108, 2023). "KRAS mutation initiates the tumour process as pancreatic intraepithelial neoplasia (panIN) with a relatively long latency or other tumour-suppressing gene mutations, and panIN progresses to pancreatic cancer." (PMID 36835437, 2023). "Additionally, sotorasib was recently reported as exhibiting noticeable anticancer activity in previously-treated patients with KRAS p.G12C–mutated advanced pancreatic cancer." (PMID 37242560, 2023). "Besides, recent efforts have focused on developing targeted therapies for pancreatic cancer, including drugs that target specific molecular alterations like the KRAS oncogene, which is frequently mutated in pancreatic cancer." (PMID 37720505, 2023). "A recent study showed that gemcitabine combined with cobimetinib might effectively treat KRAS-mutated pancreatic cancer." (PMID 37495601, 2023).
pancreatic cancer (continued). "KRAS mutations can be observed in more than 95% of pancreatic cancers." (PMID 36934248, 2023). "KRAS mutations in pancreatic cancer are often associated with Erastin, a ferroptosis activator." (PMID 38022537, 2023). "The major somatic gene mutation in pancreatic cancer is the KRAS oncogene." (PMID 36765725, 2023). "In addition, we have recently shown that the regulatory downstream targets of KRAS mutation trigger EV production in pancreatic cancers and facilitate LN metastasis in a VEGF-C-independent manner." (PMID 36971125, 2023). "Detecting KRAS mutations at an early stage may contribute to the early detection of pancreatic cancer." (PMID 36673023, 2023). "Notably, the most frequently observed mutations in PDAC involve the Kirsten rat sarcoma viral oncogene homolog gene (KRAS); the G12D and G12V mutations occur in approximately 90% of cases and are specific to pancreatic cancer." (PMID 37444534, 2023). "Additionally, hnRNPA2/B1 plays an important role in the survival of KRAS-dependent pancreatic cancer cells, wherein it directly interacts with and regulates the activity of mutated KRAS G12V and G12D to promote the PI3K/AKT/mTOR signaling pathway." (PMID 36982162, 2023). "KRAS mutations could be proven not only in the primary tumor/lesion but also in CTCs in patients with pancreatic carcinoma, often with different mutations than the originating tumor." (PMID 37511945, 2023). "KRAS is a signaling protein that drives pancreatic cancer formation mutations." (PMID 36313380, 2022). "KRAS can induce transcriptional silencing of tumor suppressor genes, and its mutations produce modified proteins that drive the occurrence and development of pancreatic cancer." (PMID 35493099, 2022). "Therefore, we first investigated the relationship between the KRAS mutation subtype and prognosis with the TCGA for pancreatic cancer patients and confirmed the prognosis benefit of the mutation type." (PMID 35785187, 2022). "Additionally, KRAS oncogene was commonly found in patients with CP and is present in almost all pancreatic cancers (90%), harboring mutations." (PMID 35365692, 2022). "Activated KRAS mutations were reported in > 90% of all pancreatic cancers." (PMID 35193647, 2022). "Pancreatic cancer patients with KRAS G12D mutation were reported with relatively poor outcomes." (PMID 34255132, 2022). "Targeting of KRAS in pancreatic cancer except for the G12C mutation may be achieved by using SOS1 inhibitors that as single drug are expected to possess limited anticancer activity." (PMID 36048281, 2022). "Consequently, there is some hope for patients with pancreatic cancer, especially for KRAS G12V gene mutated patients." (PMID 36311715, 2022). "Therefore, prostratin (PKC activator) interrupts KRAS calmodulin-binding that increases the level of Fzd8, thereby inhibiting KRAS mutation in pancreatic cancer cells." (PMID 35409064, 2022). "This could help understanding why KRAS gene amplification is associated with epithelial-to-mesenchymal transition and the degree of dedifferentiation in pancreatic cancer." (PMID 36238685, 2022). "Although it is contradictory that mTOR plays negative roles in autophagy, it shows the collaborate of mTOR and autophagy mediated by STYK1 at least in the cases of EGFR-TKIs resistance or pancreatic cancer with activating KRAS mutations and high basal autophagy." (PMID 37192859, 2022). "In particular, KRAS mutations are detected in approximately 90% of pancreatic cancer cases." (PMID 36232820, 2022). "At the same time, there is still no agent that could target KRAS G12D which is the most common KRAS mutation and is found in the majority of KRAS-mutated pancreatic tumors." (PMID 36531078, 2022).
pancreatic cancer (continued). "In addition, growing evidence revealed that KRAS is firmly implicated in the diagnosis and prognosis of pancreatic cancer and is heralded as a potential therapeutic target." (PMID 36148233, 2022). "As a preclinic drug, ARS-1620 has been also reported to disrupt the association between KRAS and Argonaute two on the plasma membrane, which may bring the therapeutic feasibility for pancreatic cancer." (PMID 35281897, 2022). "Pancreatic cancer is mainly driven by mutations in the KRAS oncogene." (PMID 36579598, 2022). "A KRAS-targeting peptide vaccine for preventing pancreatic cancer in high-risk individuals is currently under clinical test (NCT05013216), but its prophylactic efficiency is still unknown." (PMID 36224645, 2022). "Besides non-G12C KRAS mutations, amplifications of native KRAS are frequently found in pancreatic cancer." (PMID 36048281, 2022). "Pancreatic cancer cell growth depends on the activity of the mutated KRAS gene." (PMID 36091807, 2022). "In addition, it has been reported that KRAS mutations can be found in approximately 92% of pancreatic cancers, and patients with KRAS mutations showed a bad response to first-line gemcitabine-based therapy and presented a poor prognosis." (PMID 35457111, 2022). "We believe that in the presence of oncogenic KRAS, the alt-EJ pathway is a key player in tumorigenesis, and loss of alt-EJ components may prevent or delay PanIN lesions development and, ultimately, pancreatic cancer progression." (PMID 36077614, 2022). "Within a particular cancer type, the three cancers in which KRAS mutations are the predominant RAS mutations are pancreatic cancer (~ 88%), colorectal adenocarcinoma (50%) [colon adenocarcinoma (50%) and rectal adenocarcinoma (50%)], and lung adenocarcinoma (32%)." (PMID 35045886, 2022). "Furthermore, they also showed that suppression of KRAS G12V by retroviral siRNA caused loss of tumorigenicity of pancreatic cancer cells harboring KRAS G12V in a subcutaneous xenograft, proving that siRNA has power as a tumor-specific gene therapy tool." (PMID 35014625, 2022). "Oncogenic KRAS mutation is a major event in pancreatic cancer." (PMID 35565206, 2022). "Our results reveal that both the overexpression of KRAS wild-type and the activation of KRAS mutations can influence the proliferation rate in murine and human pancreatic cancer cell lines, resulting in an accelerated increase in cell number, which is a common characteristic of cancer." (PMID 36077614, 2022). "Suppression of mutated KRAS expression results in tumor regression of pancreatic tumors." (PMID 36048281, 2022). "It is estimated that almost 90% of pancreatic cancer patients have KRAS mutations." (PMID 36284087, 2022). "In a study with the MEK inhibitor cobimetinib plus gemcitabine in 13 patients with pancreatic cancer, all six patients with KRAS G12R mutated cancers achieved disease control, with one partial response and five with stable disease resulting in a median PFS of 6 months." (PMID 36124727, 2022). "In pancreatic cancers, KRAS G12D and G12V are the predominant mutations, at 40% and 32% of all KRAS mutations, respectively, while G12R mutation accounts for nearly 17% of all KRAS mutations in pancreatic cancer." (PMID 36284306, 2022). "KRAS mutation is a major propellant for the initiation and progression of pancreatic cancer." (PMID 34978469, 2022). "Notably, apart from KRAS mutation, multiple genetic and epigenomic mechanisms jointly contribute to pancreatic cancer initiation." (PMID 36224645, 2022). "Interestingly, the correlation between RAS84 expression and overall survival in pancreatic cancer, where 95% of tumours are mutated on KRAS, shows the direct link between RAS pathway-induced transcriptional activity and tumour aggressiveness." (PMID 36163168, 2022).
pancreatic cancer (continued). "Mutated KRAS is considered to be an oncogene for pancreatic cancer." (PMID 36015212, 2022). "KRAS mutations are often early events in tumourigenesis in lung and pancreatic cancers." (PMID 36284306, 2022). "Among the remaining 3 pancreatic cancer patients with discordant KRAS mutation status, two patients had the KRAS mutations (1 G12D, 1 G12R) detected in plasma samples but not detected in tissue samples, which may result from the tissue heterogeneity." (PMID 35486030, 2022). "This workflow was adopted to quantitatively detect gene alterations, i.e., EWS rearrangements in Ewing sarcoma and total KRAS transcripts including both mutated KRAS and wild‐type KRAS in pancreatic cancer, allowing for noninvasive cancer diagnosis and treatment monitoring." (PMID 35486030, 2022). "Therefore, it is conceivable that high KRAS expression is an independent risk factor which leads to a poor prognosis in pancreatic cancer patients." (PMID 34255132, 2022). "Previous studies have shown that DNA in EVs not only covers the entire genome of parental cells, but also allows identical mutations from the cells they are derived from to be detected, including clinically relevant mutations such as KRAS mutations in pancreatic cancer or BRAF in melanoma." (PMID 35805031, 2022). "Interestingly, serum EV analysis of pancreatic cancer patients showed that the presence of KRAS-specific mutations can provide unique information on patient outcome and cancer progression." (PMID 35501802, 2022). "Indeed, in human pancreatic cancers with KRAS mutations, SET/CIP2A overexpression correlates with the increased expression of IEGs, resulting in poor clinical outcomes." (PMID 36463234, 2022). "Thus, we reviewed previous studies and unexpectedly found that ITGA2 overexpression was associated with the most common KRAS mutation in pancreatic cancer." (PMID 35193647, 2022). "The KRAS mutation was one of the most frequent oncogenic events in pancreatic cancer." (PMID 36612240, 2022). "There are several types of KRAS mutations including the G12D, G12C, G12V, and G12R in pancreatic cancers which may play different roles." (PMID 35785187, 2022). "KRAS mutations are linked to more aggressive pancreatic cancers and a dismal prognosis." (PMID 36048281, 2022). "Moreover, lung and pancreatic cancer cells with KRAS mutation were also sensitive to GRB7-PLK1 inhibition in combination with MEKi." (PMID 34718347, 2022). "In PDAC, over 90% of pancreatic cancers showed about 100% frequency of KRAS mutation." (PMID 33537098, 2021). "The vast majority of pancreatic cancers (up to ≥94%) harbor mutations of the KRAS oncogene." (PMID 33405090, 2021). "We experimentally analyzed KRAS mutations using ddPCR on the same 17 plasma samples from patients with late-stage pancreatic cancer, 8 patients with early-stage pancreatic cancer, and 20 individuals without cancer, using the same plasma input volumes used for the DREAMing analysis." (PMID 33420235, 2021). "Therefore, the KRAS mutation subtype is an important factor as it can determine and predict the patient’s response to pancreatic cancer surgery and chemotherapy." (PMID 34829828, 2021). "KRAS mutational isoform status and KRAS mutational status per se (KRAS wild type versus KRAS mutant) are associated with different clinical outcomes including overall survival in pancreas cancer." (PMID 33405090, 2021). "In addition, our genetic analysis using target sequencing was reliable as we were able to detect KRAS mutations in pancreatic tumor samples at a high frequency as in previous studies." (PMID 34798839, 2021).